ANXA4 (annexin A4)
Diseases named in the same sentence as ANXA4 in open-access papers (continued):
Sharing a sentence is not in itself a finding about the gene and the disease.
ovarian clear cell cancer (5 papers, 2014 to 2024). An invasive malignant neoplasm that arises from the ovary and is characterized by a predominance of clear and hobnail malignant epithelial cells. "Binding between ANXA4 and Vimentin promotes the proliferation, invasion, and migration of ovarian clear cell carcinoma, and inhibits cell apoptosis by activating the ERK and NF-kB pathways." (PMID 31474227, 2019). "Annexin A4 contains Lewis y structure, Lewis y antigen modification of annexin A4 enhances its interaction with NF-kB p50, which promotes ovarian clear cell carcinoma malignancy progression." (PMID 29296226, 2017). "Any interactions between annexin A4 and NF-kB p50 in ovarian clear cell carcinoma were detected by co-immunoprecipitation." (PMID 29296226, 2017). "We recently reported that annexin A4 (ANXA4) is overexpressed in ovarian clear cell carcinoma and induces chemoresistance to platinum-based drugs." (PMID 25277200, 2014). "The TCGA database mainly focused on ANXA4 expression level in ovarian serous cystadenocarcinoma, which may have led to a discrepancy with our results that showed the highest expression level of ANXA4 in ovarian clear cell carcinoma." (PMID 31474227, 2019).
clear cell renal carcinoma (4 papers, 2008 to 2017). A malignant epithelial neoplasm of the kidney characterized by the presence of lipid-containing clear cells within a vascular network. "In renal carcinoma, the positive expression rate of ANXA4 in renal clear cell carcinoma is as high as 87.4%, significantly higher than for other types of pathology." (PMID 29296226, 2017). "Renal clear cell carcinoma also shows overexpression of annexin A4 and this seems to be related to the metastatic potential of this type of tumour." (PMID 18071363, 2008). "There is increased expression of annexin A4 in renal clear cell carcinoma." (PMID 18071363, 2008).
colon carcinoma (4 papers, 2013 to 2022). "Cai's study also showed that ANXA4 is over-expressed and its phosphorylation modification is significantly increased in colon carcinoma tissues relative to normal colon tissues; and that ANXA4 expression is correlated with the late stages of colon cancer and poor prognosis." (PMID 29296226, 2017).
glioma (3 papers, 2020 to 2024). A benign or malignant brain and spinal cord tumor that arises from glial cells (astrocytes, oligodendrocytes, ependymal cells). "In particular, ANXA4 is possibly involved in microRNA-7 (miR-7) induced migration and invasion inhibition of glioma." (PMID 38639785, 2024). "This reduction of ANXA4 inhibited migration and invasion capacities of glioma cell lines U251, U87, and A172 and reduced the tumor migration of U251 cells in nude mice." (PMID 38639785, 2024). "ANXA4 expression is increased in various clinical epithelial tumors, including gastric, colorectal, pancreatic, breast, and laryngeal cancers, and gliomas." (PMID 38639785, 2024). "Consequently, it can be inferred that miR-7 suppresses the malignant behavior of glioma cells, at least in part, by impacting the expression of ANXA4." (PMID 38639785, 2024). "The expression of ANXA4 was inhibited 3.5-fold by miR-7 overexpression in glioma cells." (PMID 38639785, 2024). "Furthermore, the overexpression of ANXA4 has been identified in various malignant tumors, including glioma." (PMID 33628783, 2021). "Our results are similar to those of a previous study, indicating that ANXA4 may be a vital characteristic in the growth of glioma cells under the stimulation of BM-MSCs." (PMID 33628783, 2021).
lymph node metastasis (3 papers, 2016 to 2021). "High expression of ANXA4 was positively associated with lymph node metastasis (P < 0.001), invasion depth (P = 0.028), and TNM stage (P = 0.010)." (PMID 27491820, 2016). "Chi-square test analysis showed a positive correlation between high ANXA4 expression and lymph node metastasis in CRC patients (n=138)." (PMID 33761465, 2021). "COX prognostic multi-factor analysis was carried out for clinical stages, lymph node metastasis, residual tumor sizes, ANXA4 expression levels, and Lewis y antigen expression levels." (PMID 29296226, 2017). "The strong ANXA4 expression rate in the lymph node metastasis group was 90.0%(9/10), which was higher than the group without lymph node metastasis(58.1%, 43/74), but not significant, (P<0.05, P=0.109)." (PMID 29296226, 2017). "In the current study, we showed that overexpression of ANXA4 correlated well with invasion depth as well as lymph node metastasis, and predicted poor survival in GBC patients." (PMID 27491820, 2016). "Multivariate Cox proportional hazards analysis revealed that ANXA4 expression was an independent prognostic marker for OS in GBC patients (P < 0.001), and that invasion depth (P < 0.001) and lymph node metastasis (P = 0.003) were also significantly associated with OS." (PMID 27491820, 2016).
non-small cell lung carcinoma (3 papers, 2018 to 2021). A group of at least three distinct histological types of lung cancer, including non-small cell squamous cell carcinoma, adenocarcinoma, and large cell carcinoma. "A recent study indicated that downregulation of ANXA4 by toosendanin could mediate cisplatin sensitization in non-small cell lung cancer." (PMID 34540918, 2021).
squamous cell carcinoma (3 papers, 2016 to 2025). A carcinoma arising from squamous epithelial cells. "Serum albumin, HSP (Heat shock protein) 27, gamma actin, SCC (Squamous cell carcinoma) 1, and Annexin A4." (PMID 40256126, 2025). "The identified proteins were serum albumin, HSP (Heat shock protein) 27, gamma actin, SCC (Squamous cell carcinoma) 1, and Annexin A4." (PMID 34181340, 2021). "Serum albumin, Heat shock protein 27 (HSP 27), gamma actin, squamous cell carcinoma (SCC) 1, and Annexin A4 (ANXA4) were identified proteins and have a positive association with OSCC development." (PMID 34181340, 2021). "ANXA2 expression was more prominent in squamous cell carcinoma (p < 0.001), whereas ANXA4 was more highly expressed in adeno/adenosquamous carcinoma (p < 0.001)." (PMID 27402115, 2016). "ANXA2 was more highly expressed in squamous cell carcinoma, whereas ANXA4 was expressed more prominently in adeno-/adenosquamous carcinoma (p < 0.001 and p < 0.001, respectively)." (PMID 27402115, 2016). "The positive correlation between mRNA and protein expression was more prominent in squamous cell carcinoma for ANXA2 and in adenocarcinoma for ANXA4, suggesting that these ANXs potentially have different roles according to cervical cancer cell type." (PMID 27402115, 2016). "We also found that ANXA2 and ANXA4 were differentially expressed according to cell type, suggesting that each ANX potentially has a different role in squamous cell carcinoma or adenocarcinoma in patients with cervical cancer." (PMID 27402115, 2016).
bladder cancer (2 papers, 2021 to 2025). "Studies show that ANXA4 is overexpressed in bladder cancer tissues, especially in the luminal subtype, and its increased expression promotes cell cycle progression and inhibits apoptosis, correlating with poorer prognosis." (PMID 41463032, 2025). "The expression of ANXA1, ANXA2, ANXA3, ANXA5, ANXA6, ANXA8, and ANXA13 was closely related to basal-subtype bladder cancer, while the expression of ANXA4, ANXA9, ANXA10, and ANXA11 was closely related to luminal-subtype BC." (PMID 34484309, 2021). "We also analyzed the possible role of ANXA-L (ANXA4, ANXA9, ANXA10, and ANXA11) in the regulation of luminal bladder cancer." (PMID 34484309, 2021). "Despite extensive research on CYTB, ANXA4, and SBP1 in bladder cancer tissue, direct studies on C1QC’s role in bladder cancer are limited, though its immune regulatory functions suggest it could influence tumor progression." (PMID 41463032, 2025).
cervical carcinoma (2 papers, 2016 to 2017). A carcinoma arising from either the exocervical squamous epithelium or the endocervical glandular epithelium. "The present study was to investigate the clinical significance of annexin A2 (ANXA2) and annexin A4 (ANXA4) expression in cervical cancer." (PMID 27402115, 2016). "In the present study, we investigated the prognostic significance of ANXA2 and ANXA4 in cervical cancers using immunohistochemistry and quantitative image analyses." (PMID 27402115, 2016). "Multivariate analysis indicated that ANXA2+ (HR = 2.72, p = 0.003) and ANXA2+/ANXA4+ (HR = 2.69, p = 0.039) are independent prognostic factors of disease-free survival in cervical cancer." (PMID 27402115, 2016). "In conclusion, our results show that ANXA2 and ANXA4 protein expression, alone or in combination, are independently poor prognostic factors of survival in patients with cervical cancer." (PMID 27402115, 2016). "ANXA2 and ANXA4 immunohistochemical staining were performed on a cervical cancer tissue microarray consisting of 46 normal cervical epithelium samples and 336 cervical cancer cases and compared the data with clinicopathological variables, including the survival of cervical cancer patients." (PMID 27402115, 2016). "However, knowledge on the clinical and prognostic significance of ANXA2 and ANXA4 expression in patients with cervical cancer is limited." (PMID 27402115, 2016). "Furthermore, we demonstrated that high ANXA2 and ANXA4 expression predicted poor survival in patients with cervical cancer, which was supported by the improved predictive power of a model using combined clinical-ANXA2/ANXA4-variables." (PMID 27402115, 2016). "No report has evaluated ANXA4 expression and prognosis of cervical cancer." (PMID 27402115, 2016).
clear cell carcinoma (2 papers, 2014 to 2015). "As previously reported, ANXA4 is significantly upregulated in clear cell carcinoma cell lines (OVTOKO, OVISE and RMG-I) compared with other histological types (serous and mucinous adenocarcinoma cell lines: A2780, OVCAR3, OVSAHO and MCAS)." (PMID 25277200, 2014). "ANXA4 expression was strong in clear cell carcinoma cell lines (OVTOKO, OVISE and RMG-I) compared with serous adenocarcinoma cell lines (A2780, OVCAR3 and OVSAHO) and a mucinous adenocarcinoma cell line (MCAS)." (PMID 25277200, 2014).
COVID-19 (2 papers, 2020 to 2022). A disease caused by infection with severe acute respiratory syndrome coronavirus 2. "Within the salivary proteins that were significantly increased in patients with COVID-19, five contributed most on the model: CAZA1, ACTN4, TGM3, CO4A, and ANXA4." (PMID 35760827, 2022). "Specifically, within upregulated, CAZA1, CO4A, ANXA4, and immunoglobulin kappa variable 3–20 (IGKV3-20) were significantly increased in mild disease COVID-19 while ACTN4 and fibrinogen beta (FGB) chain were significantly increased in severe COVID-19 individuals." (PMID 35760827, 2022). "ECM-associated proteins include several anticoagulant proteins (e.g. the annexin family members ANXA3, ANXA4, ANXA5, and ANXA8L1) of ECM-affiliated proteins were markedly diminished, which is consistent with the results indicating coagulation dysfunction in the COVID-19 patients." (PMID 33060566, 2020).
endometriosis (2 papers, 2020 to 2024). The growth of functional endometrial tissue in anatomic sites outside the uterine body. "Five genes (ANXA4, CDA, CDK10, DST, and HSP90AB1) from the catalogue were reported to be associated with endometriosis at two omics levels, for example ANXA4 gene at transcriptomics and ANXA4 at proteomics level." (PMID 32474803, 2020). "ANXA4 was shown to be upregulated in III/IV compared to I/II endometriosis in both proliferative and mid-secretory samples but downregulated in early-secretory samples." (PMID 37789126, 2024). "Repeated genes associated with P-phase (ACTB, ANXA4, BPIFB1, EPHX1, MUC5B, PRDX2, and VIM) could indicate stronger genetic causes associated with pathophysiology of endometriosis." (PMID 32474803, 2020).
head and neck cancer (2 papers, 2009 to 2016). A primary or metastatic malignant neoplasm affecting the head and neck. "The expression of annexin A4, 5, and 8 in head and neck cancer has been reported in this study for the first time, which was consistent with the results obtained in other studies concerning their expression in other cancers." (PMID 19691830, 2009). "The level of ANXA2 mRNA expression is relatively high in the cervical and head/neck cancers which are largely correlated with HPV infection, whereas ANXA4 mRNA expression showed intermediate level in the both cancers." (PMID 27402115, 2016).
Hepatic fibrosis (2 papers, 2025). The presence of excessive fibrous connective tissue in the liver. "Additionally, MFSD6 and ANXA4 were positively correlated with ALP, ALT, and hepatic fibrosis, indicating their roles in liver function." (PMID 41245305, 2025).
lupus (2 papers, 2014 to 2021). "However, the expression of Anxa4 and TLR2 were increased in M-MDSCs, INK128 could inhibit Anxa4 and TLR2 expression in M-MDSCs in pristane-induced lupus mice." (PMID 34282122, 2021).
mesothelioma (2 papers, 2012 to 2016). A usually malignant and aggressive neoplasm of the mesothelium which is often associated with exposure to asbestos. "In clear cell carcinoma of the ovary and mesothelioma cells, ANXA4 expression is elevated and associated with resistance to treatment with carboplatin, and is considered to be a biomarker for susceptibility to cisplatin." (PMID 22970268, 2012). "By comparing these datasets, we found 3 genes that were elevated in 3D compared to 2D as well as in mesothelioma compared to normal tissue: argininosuccinate synthetase 1 (ASS1), annexin A4 (ANXA4) and the major vault protein (MVP)." (PMID 26982031, 2016).
mucinous adenocarcinoma (2 papers, 2013 to 2014). An invasive adenocarcinoma composed of malignant glandular cells which contain intracytoplasmic mucin. "Mucinous adenocarcinomas also showed high expression of ANXA4, as did their benign counterpart, mucinous adenomas." (PMID 24244679, 2013). "In carcinoma cases, although few cases were available for IHC, all four mucinous carcinomas and two of six endometrioid carcinomas showed high levels (IHC score 4 or greater) of ANXA4 expression." (PMID 24244679, 2013).
Alzheimer disease (1 paper, 2012). A progressive, neurodegenerative disease characterized by loss of function and death of nerve cells in several areas of the brain leading to loss of cognitive function such as memory and language. "Recent studies have shown that the increased amount of ANXA4 is not only associated with cancer but also Alzheimer’s disease, heart failure and cell lesion caused by ethanol." (PMID 22970268, 2012).
atherosclerosis (1 paper, 2024). A disease characterized by the build-up of fatty material and calcium deposition in the arterial wall resulting in partial or complete occlusion of the arterial lumen. "The gene list included well-known atherosclerosis-associated genes Serpina3,42Cemip,43Thbs1,44Lum,45 and Spp146,47 but also novel genes without previous association to SMC function in atherosclerosis, such as Anxa4, Cd276, Itih4, Myof, Pcdh11x, Rab31, Serpinb6b, Slc35e4, Slc8a3, and Spink5." (PMID 38289873, 2024). "Moreover, we identified several novel genes not previously linked to SMCs in atherosclerosis, such as Anxa4, Cd276, inter-alpha-trypsin inhibitor-4 (Itih4), Myof, Pcdh11x, Rab31, Serpinb6b, Slc35e4, Slc8a3, and Spink5." (PMID 38289873, 2024).
bladder tumors (1 paper, 2021). "ANXA2, ANXA3, ANXA4, ANXA8, and ANXA9 were significantly increased in bladder tumor tissues, while ANXA6, ANXA7, and ANXA11 were significantly decreased." (PMID 34484309, 2021).
cervical clear cell carcinoma (1 paper, 2017). "Our results also suggest that ANXA4 has a higher expression rate in endometrial and cervical clear cell carcinoma than in other types of pathology (results to be published)." (PMID 29296226, 2017).
dysferlinopathy (1 paper, 2024). "Moreover, we observe significant associations between the protein expression of ANXA1, ANXA2, ANXA4, ANXA5, LMNA, PYGM, and the extent of histopathologic changes in muscle biopsies from patients with dysferlinopathy, validated through immunoblotting and immunofluorescence assays." (PMID 39350328, 2024).
endometrial carcinoma (1 paper, 2015). A malignant tumor arising from the epithelium that lines the cavity of the uterine body. "Exposure of an AnxA4-overexpressing endometrial carcinoma cell line to platinum drugs caused relocalization of AnxA4 from the cytoplasm to the membrane fraction, and colocalization of P-type ATPase ATP7A (a copper and platinum transporter) to cell membranes." (PMID 26675567, 2015).
gallbladder tumor (1 paper, 2016). "Real-time polymerase chain reaction (RT-PCR) analysis indicated that ANXA4 mRNA was expressed at significantly higher levels in all gallbladder tumor specimens compared with normal tissues." (PMID 27491820, 2016).
gastric adenocarcinoma (1 paper, 2013). "Only one study was found in the literature on the relationship between cell proliferation and ANXA4 in cancer cells; Lin and colleagues recently found that ANXA4 overexpression or attenuation by siRNA in a gastric adenocarcinoma cell line, AGS, indicated its function to be a growth activator." (PMID 24244679, 2013).
gastric tumors (1 paper, 2012). "In respect to cancer, ANXA4-overexpression has been observed in cancers of various origins, including gastric tumors associated with Helicobacter pylori infection." (PMID 22970268, 2012). "We have previously reported that ANXA4 is overexpressed in H. pylori infected gastric tumor tissue." (PMID 22970268, 2012). "Despite this correlation, the role of ANXA4 in the progression of gastric tumors remains unclear." (PMID 22970268, 2012).
heart failure (1 paper, 2012). Inability of the heart to pump blood at an adequate rate to meet tissue metabolic requirements. "Moreover, ANXA4 is an intracellular Ca2+ sensor, and Ca2+ plays an important role in neurotoxicity and heart failure." (PMID 22970268, 2012).
kidney cancer (1 paper, 2023). Primary or metastatic malignant neoplasm involving the kidney. "Annexin A4 (ANXA4), a calcium-regulated phospholipid-binding protein, has emerged as a potential biomarker candidate in kidney cancer." (PMID 38201450, 2023).
liver cirrhosis (1 paper, 2020). "ROC curve analysis was performed to assess the diagnostic performance of ANXA4 in discriminating patients with HCC from those with liver cirrhosis." (PMID 32986366, 2020). "Serum ANXA4 level was significantly higher in HCC patients compared to patients with liver cirrhosis and healthy controls (188, IQR 42-428 and 23, IQR 24-33 and and 21, IQR 22-24 ng / ml, respectively)." (PMID 32986366, 2020). "Also, we found that ANXA4 can differentiate between HCC and liver cirrhosis since we found that the levels of ANXA4 were significantly higher in patients with HCC than in cirrhotic patients." (PMID 32986366, 2020).
malignant mesothelioma (1 paper, 2021). A malignant neoplasm of the pleura or peritoneum, arising from mesothelial cells. "In a previous study, we identified that the malignant mesothelioma cell lines in which the Annexin A4 gene was overexpressed or knocked down showed significantly inhibition or enhancement of the cytotoxicity of cisplatin, demonstrating that Annexin A4 is involved in cisplatin resistance." (PMID 33504115, 2021).
medullary carcinoma (1 paper, 2023). "Annexin A4 is reported to be highly expressed in follicular and medullary carcinoma but not in other thyroid carcinoma subtypes—precisely the opposite of our results." (PMID 37833989, 2023).
Miscarriage (1 paper, 2024). A pregnancy that ends at a stage in which the fetus is incapable of surviving on its own, defined as the spontaneous loss of a fetus before the 22th week of pregnancy. "Furthermore, the ANXA4 gene may play an important role in pregnancy, but there are currently no reports on whether it is involved in the occurrence of miscarriage." (PMID 39399103, 2024).